TNF (tumor necrosis factor)
Diseases named in the same sentence as TNF in open-access papers (continued):
Sharing a sentence is not in itself a finding about the gene and the disease.
COVID-19 (continued). "Based on these lines of evidence, the use of anti-TNF-α monoclonal antibodies, largely employed for autoimmune diseases, has been proposed in COVID-19 with the aim of inhibiting this cytokine and thus reducing the inflammatory effects triggered by this cytokine." (PMID 33669218, 2021). "We found that severe COVID-19 patients displayed, as extensively already reported, high level of circulating inflammatory cytokines, including IL-6, TNF-α, IL-1β and chemokines such as CXCL-10, CCL-2 and CXCL-8 contributing to the diffuse inflammatory status and the so-called cytokine storm." (PMID 34473805, 2021). "Thus, our data support the concept of using anti-TNF therapy in COVID-19, as has been suggested by observational clinical data." (PMID 34445140, 2021). "The authors of the study concluded that homogenous hyperinflammatory innate immune responses (higher plasma concentrations of TNF-α and IL-6) in COVID-19 patients are combined with defective adaptive immune responses due to profound lymphopenia, exhausted T cells and decreased functionality." (PMID 34945111, 2021). "Therefore, the effectiveness of TNF inhibitors in patients with moderate COVID-19 should be initially assessed as soon as possible upon hospital admission." (PMID 34725309, 2021). "In addition to important modifications in protein cargo, we demonstrate that HDLs from COVID-19 patients were less protective for endothelial cells stimulated with TNFα than HDLs from healthy subjects." (PMID 33504824, 2021). "To ascertain if the therapeutic effect of Xanthohumol relieved virus-induced cytokine dysregulation, we determined the expression levels of IL-6, IL-10, and TNF-α, which are prognostic markers for severe COVID-19, as well as other major pro-inflammatory cytokines including IFN-γ." (PMID 34702802, 2021). "Baricitinib, a TNF-α agonist and a drug for RA, also has been approved recently to treat COVID-19." (PMID 33535459, 2021). "It is therefore suggested that anti-TNF treatment could reduce inflammation-driven capillary leak in COVID-19; and may reduce the need for mechanical ventilation as well as mortality." (PMID 33995033, 2021). "It is known that COVID-19 is characterized by elevated levels of TNF-α and IL-6, which may directly stimulate CMV reactivation." (PMID 34830421, 2021). "Interestingly, Jain and co-authors analysed the vitamin D level in both asymptomatic and critically ill COVID-19 patients and its correlation with inflammatory markers (IL-6; TNF-α, and serum ferritin)." (PMID 33530467, 2021). "The elevated levels of cytokines like TNF-α and Il-1 were noticed in COVID-19 patients." (PMID 33981235, 2021). "Of relevance, anti-TNF therapy may not only inhibit the hyperinflammatory state but also may reduce NET formation in COVID-19 patients." (PMID 34803441, 2021). "The level of TNF-α was found to be increased in the blood plasma of patients with COVID-19." (PMID 34603758, 2021). "In particular, IL-8, IL-6, and TNF-α levels were found to be significantly elevated in the sera of patients with COVID-19 compared with those of healthy donors or with plasma isolated from chimeric antigen receptor-modified T cell-treated patients with no cytokine release syndrome." (PMID 33572938, 2021). "Plasma profiling identified multiple features shared by MIS-C, Kawasaki Disease and COVID-19 and that therapeutic inhibition of IL-6 may be preferable to IL-1 or TNF-α." (PMID 34632327, 2021). "Further, anti-TNF therapy might reduce COVID-19-induced thrombosis, which could be attributed to the depletion of D-dimer and pro-thrombin fragments." (PMID 33714258, 2021). "Furthermore, a reduced production of TNF-α by stimulated monocytes from COVID-19 patients was noticed." (PMID 33995342, 2021).
COVID-19 (continued). "The CpG sites are common targets of viral genome and can be recognized by Toll-like receptors (TLRs) that results in release of pro-inflammatory cytokines including type- I interferon, IL-6, IL-12 and TNF-α those play key role in severe COVID-19 including lung tissue damage." (PMID 34458642, 2021). "In addition, previous clinical data revealed that IL-6 and TNF-α were the most critical cytokines detected in patients with severe COVID-19 symptoms." (PMID 35401158, 2021). "Patients with COVID-19 have elevated levels of various cytokines such as IL-2, IL-4, IL-6, and IL-10, TNF-α, IFN-γ and may present with the so-called cytokine storm." (PMID 34684384, 2021). "High concentrations of TNF-α were reported in both plasma and tissues of patients with COVID-19." (PMID 34359931, 2021). "Interestingly, a lower odd of hospitalization was reported in COVID-19 patients treated with TNF inhibitors for rheumatic diseases (OR, 0.40; 95% CI, 0.19 to 0.81)." (PMID 34959657, 2021). "These clinical findings indicated that lymphocytopenia in COVID-19 patients may be due to cytokine storm (IL-1, IL-6, and TNF-α) as well as pathological effects of leukocytes and macrophages." (PMID 33746897, 2021). "Serum IL-1β and TNF-α levels are obviously elevated in patients with severe COVID-19." (PMID 33404925, 2021). "In a kind of positive feedback loop, the ADAM17-mediated shedding activity appears to be enhanced by the binding of the viral spike protein to ACE2, and to be stimulated by AngII and the pro-inflammatory cytokines interleukin (IL)-1β and TNF-α, whose secretion is elevated in COVID-19 patients." (PMID 34685735, 2021). "Therefore, it is necessary to detect the levels of D-dimer and IL-6, TNF-α, and IL-1 to prevent and predict the intestinal coagulation disease of COVID-19." (PMID 34858386, 2021). "Levels of IL-6 and TNF both independently predict COVID-19 disease severity and mortality and may be important therapeutic targets." (PMID 34341776, 2021). "Moreover, the tumor necrosis factor (TNF) identified in this study was reported in the Lancet to be an important therapeutic target for COVID-19." (PMID 33413329, 2021). "COVID-19 patients who succumb to pneumonia and hypoxia had one hallmark feature of the profound inflammatory state that marked elevation of serum inflammatory cytokines (IL-6, IFN-γ, IL-1β, TNF-α and TGF-β) and chemokines (CCL2, CCL5, CXCL8 and CXCL10)." (PMID 34313585, 2021). "The association of higher CRP with worse outcomes may be due to the severity of the disease consistent with the ‘cytokine storm’ theory of COVID-19, where the innate immune system is activated releasing TNF-alpha, IL-6 and IL-1." (PMID 33683344, 2021). "Furthermore, patients with COVID-19 exhibited hyper-inflammatory signatures across all types of cells among PBMCs, particularly upregulation of the TNF/IL-1β-driven inflammatory response and type I IFN responses." (PMID 33674719, 2021). "Previous studies have also reported that overproduction of TNF-α is associated with poor disease outcomes in MERS-CoV and SARS-CoV, while administration of anti-TNF-α antibody (certolizumab) may have positive effects on COVID-19 patients." (PMID 34276659, 2021). "Therefore, more research and clinical trials are needed to confirm the effectiveness of TNF-α blocking treatment in COVID-19." (PMID 34938746, 2021). "However, both severe (7.18 ± 0.94 pg/ml, P<0.0001) and mild (5.73 ± 0.26 pg/ml, P<0.0001) COVID-19 patients had significantly higher serum TNF-α concentrations than healthy subjects (0.2 ± 0.03 pg/ml)." (PMID 33968010, 2021). "This miRNA was shown to reduce the expression of IL-6 in TNF-α stimulated MH7a cells and so its reduction may be partially responsible for the characteristic IL-6 increase seen in COVID-19 patients." (PMID 34320031, 2021). "HDL from patients with COVID-19 showed less protection in TNF-α treated endothelial cells." (PMID 34335279, 2021).
COVID-19 (continued). "A clinically relevant aspect of the pandemic COVID-19 is its ability to induce the so-called cytokine storm (CS) that consists of interleukin-1 (IL-1), interleukin-6 (IL-6), interleukin-8 (IL-8), and tumor necrosis factor-alpha (TNF-α)." (PMID 33850936, 2021). "IL-7 treatment did not significantly increase the frequency of MAIT cells expressing TNF-α or granzyme B in COVID-19 patients, but it successfully increased both the perforin expression level (MFI) (p = 0.001) and the frequency of MAIT cells expressing perforin (p = 0.001)." (PMID 34238985, 2021). "As there is an inverse relationship between TNF-α expression and T cell recruitment, similar to IL-1RA and IL-6, elevated TNF-α expression may further contribute to inflammatory progression of COVID-19 patients to develop ARDS or AKI." (PMID 34131192, 2021). "Our study suggests that andrographolide could bind with TNF and NFkB1 proteins, block TNF-induced cytokine storm in COVID-19 patients, and warrant further experimental validation." (PMID 34248936, 2021). "The role of IL-6, IL-1β, and TNFα in those suffering with COVID-19 is somewhat contradictory, with conflicting reports of these markers being linked to both mild disease and more severe cases typified by the occurrence of an inflammatory syndrome and a dysregulated proinflammatory response." (PMID 35222355, 2021). "MAIT cells isolated from COVID-19 patients expressed significantly higher levels of the pro-inflammatory cytokines TNFα and IL-17A, as well as of the cytolytic protein granzyme B compared to healthy controls ex vivo, while ex vivo expression of IFNγ and perforin was unchanged." (PMID 33546489, 2021). "Furthermore, a recent analysis indicated higher systemic levels of IL-2, IL-7, IL-10, monocyte chemoattractant protein-1 (MCP-1), macrophage inflammatory protein-1A (MIP-1A), and TNF-α, among critically ill COVID-19 patients." (PMID 33566210, 2021). "Indeed, among the deceased patient of COVID-19, the level of TNF-α, IL-6, IL-1β, and IL-8, were the highest when compared to recovered cases." (PMID 33632295, 2021). "Novel anti-TNFα and anti-IL-6 cannabis extracts can be useful additions to the current anti-inflammatory regimens to treat COVID-19, as well as various rheumatological diseases and conditions, and ‘inflammaging’ - the inflammatory underpinning of aging and frailty." (PMID 33465050, 2021). "However, in epithelial cells from BALs of patients infected with COVID-19, IL-6 or TNF mRNAs were barely detectable." (PMID 33585804, 2021). "This complex is epigenetically subverted to induce abnormally elevated levels of interferons (IFNs) and pro-inflammatory cytokines, such as tumour necrosis factor alpha (TNF-α) and interleukins (ILs), associated with critically ill and ICU admission of COVID-19 patients." (PMID 34691068, 2021). "Monocytes were negatively correlated with IL-2, IL-4, and TNF-α in the COVID-19 severe group." (PMID 34712741, 2021). "However, severe COVID-19 patients exhibit sustained systemic hyper-inflammation state and cytokine storms, characterized by lymphopenia and the elevation of TNF-alpha, IL-1, and IL-6." (PMID 34344306, 2021). "IL-6, MCP-1, TNFα and other immune markers, particularly those involved in myeloid cell recruitment and function, have been identified as markers that are important in the development of COVID-19." (PMID 34452519, 2021). "TNF is a major mediator of pulmonary edema and multi-organ failure in cases of severe COVID-19." (PMID 35264975, 2021). "The high percentage of CD14+CD16+ monocytes in severe COVID-19 patients have been demonstrated in two studies, which are specialized in producing inflammatory mediators including GM-CSF and IL-6, IL-10, and TNF-α." (PMID 33757410, 2021).
COVID-19 (continued). "ERK1/2 activated by the combined action of RBD and cytokines crucial for the development of severe COVID-19, i.e. interferon-gamma (IFNγ) and tumour necrosis factor-α (TNFα), are more effectively inactivated by CO2 than by dexamethasone or acetylsalicylic acid in human bronchial epithelial cells." (PMID 34741187, 2021). "Surprisingly, biologic treatment with tumor necrosis factor (TNF) antagonist was not an independent risk factor for COVID-19." (PMID 33692973, 2021). "Some type 2 cytokines (IL-4, IL-9, IL-13, etc.)have inhibitory effects on the production of proinflammatory cytokines (IL-1β, IL-6, TNF-α, etc.), the overactivation of which have been proposed as a potential key mechanism of protection against COVID-19 to some extent." (PMID 35082829, 2021). "These cells, populated in the late memory fraction (IgD− CD27−, also known as double-negative B cells), release inflammatory molecules like TNF-α, IL-8, and IL-6, have been linked to autoimmune illness, chronic viral disease, and COVID-19." (PMID 35822018, 2021). "RNA sequencing analysis of macrophages stimulated with sera from anti-spike IgG positive COVID-19 patients showed induction of a pro-inflammatory gene program, as highlighted by induction of TNF, interleukins, chemokines, and macrophage differentiation factors." (PMID 33979301, 2021). "The increased systemic values of TNF-α, IL-1β, IL-6, IL-12, IL-23, and IL-33 support the prevalence of innate pro-inflammatory mediators in the serum of subjects with a severe form of COVID-19." (PMID 34917631, 2021). "Therefore, the administration of anti-TNF-α, such as adalimumab, would be beneficial for COVID-19 patients." (PMID 34812049, 2021). "Moreover, severe COVID-19 induces the expression of Tbet that preferentially controls Th1 responses and downregulates the inflammatory cytokines TNFα, IL-1β." (PMID 34512643, 2021). "Hence, the potential of anti-TNF-α drugs is of greatest interest, and their use in hospitalised COVID-19 patients is highly discussed as a possibly very effective treatment option, especially if given in the early stage of the disease." (PMID 33445810, 2021). "Importantly, the cytokine profile described in COVID-19-Patients shows large similarities with the cytokine profile of α7nAChRs dysregulated macrophages i.e. massively secreting IL-1β, IL-6, tumor necrosis factor alpha (TNF α) α and IL-18 among others." (PMID 33510335, 2021). "In a recent study we showed that COVID-19 patients generate a large number of polyfunctional antigen-specific T cells, expressing at least two of the pro-inflammatory Th1 cytokines TNF, IL-2, IFNγ or the cytotoxic granzyme B, after stimulation with M, N or S OPPs." (PMID 34228322, 2021). "Moreover, other anticytokine agents, such anakinra, an IL-1 receptor antagonist, and anti-TNF-α agents also have potential as treatments for COVID-19." (PMID 34088317, 2021). "COVID-19 relevant inflammatory cytokines like interleukin (IL)-6, IL-8, tumor necrosis factor-α (TNF-α), monocyte chemoattractant protein-1 (MCP-1) or IL-1β, and anti-inflammatory cytokines like IL-10 or IL-1 receptor antagonist (IL-1ra) were shown to correlate with disease severity." (PMID 34177967, 2021). "Therefore, NF-κB/TNF-α is extensively targeted for the treatment of inflammation and increasing evidence indicates that many edible and medicinal plants used in COVID-19 alleviated inflammation via the NF-κB/TNF-α signaling pathway." (PMID 33995078, 2021). "Anti-TNF-alpha antagonists etanercept and adalimumab could be also administrated in moderate COVID-19 with pneumonia in order to downregulate IL-1 and IL-6 levels as potential endpoints." (PMID 34205487, 2021). "Notably, out of 27 differentially expressed proteins, 15 were found to be regulated by IL-1β, IL-6, or tumor necrosis factor (TNF), which are seen at markedly higher levels in most severe COVID-19 patients." (PMID 34667241, 2021).
COVID-19 (continued). "We hypothesize that anti-Type II interferon (like JAK inhibitors) and anti-TNF combinatorial treatment might prove effective at inhibiting the cytokine storm driving acute respiratory distress syndrome in patients with severe COVID-19." (PMID 33879239, 2021). "Moreover, IL-6 and TNF-α levels have been shown to predict disease severity, clinical progression, and death in hospitalized COVID-19 patients." (PMID 34593760, 2021). "NDG from severe/critical COVID-19 patients may be primed in vivo to spontaneously produce NETs, since they are exposed to IL-6, IL-2, IL-7, TNF, CXCL10, MCP-1, MIP1a, GM-CSF and M-CSF during the cytokine storm." (PMID 34685525, 2021). "In addition, the factors involved in pulmonary fibrosis such as TGF-β, interleukin-6 (IL-6), and tumor necrosis factor-α (TNF-α) were increased in patients infected with COVID-19." (PMID 35069217, 2021). "Therefore, the XBJ injection can regulate the TNF signal pathway through AKT1, so that it has anti-inflammation and anti-virual effects, and thus the potential to reduce the inflammation caused by COVID-19." (PMID 34077310, 2021). "COPD patients with severe COVID-19 had elevated serum levels of various inflammatory cytokines including IL-2R, IL-6, IL-8, IL-10, and TNF-α suggesting there may be global alterations in the immune response." (PMID 34262047, 2021). "Our findings suggest that, TNF-α may participate in the cytokine storm and aggravate the myocardial damage in COVID-19 patients." (PMID 34576032, 2021). "The pathogenesis of the acute pulmonary injury related to COVID-19 is similar to that occurring in other disorders that induce hyperinflammatory state with a release of high amounts of pro-inflammatory cytokines, mainly, IL-1, IL-6 and TNF-α." (PMID 33925423, 2021). "Besides, the activation of TNF and NF-кB signaling pathways were identified as the novel changes in the pathogenesis of COVID-19." (PMID 33444408, 2021). "Pathway analysis suggested that luteolin may regulate the Toll-like receptor signaling pathway, MAPK signaling pathway, TNF signaling pathway, and so on to combat COVID-19/asthma comorbidity." (PMID 35069542, 2021). "IL-10, which is known as a suppressor in the initiation phase of inflammation during COVID-19 and correlated strongly with proinflammatory IL-6 (r=0.5, p<0.0001) and TNF-α (r=0.6, p<0.0001), probably performing an immune-inhibitory mechanism as a negative feedback inflammation loop." (PMID 34858428, 2021). "Vitamin D may also help to reduce the severity of inflammatory reactions by inhibiting pro-inflammatory cytokines such TNF-α and IL-6, which are involved in the development of cytokine storm in COVID-19-related ARDS." (PMID 34884440, 2021). "First, as TNF-α is a key player in many acute inflammatory reactions, acting as an amplifier of inflammation, algae-based anti-TNF blockade has the potential to assist in treating other virus-induced CS, such as COVID-19, influenza, and autoimmune-related inflammatory diseases." (PMID 33566210, 2021). "Furthermore, mean concentrations of all five cytokines in the influenza (CS) group and IL-6, IL-8, TNF-α in the burn group were significantly greater than in COVID-19 patients (p < 0.01)." (PMID 33921604, 2021). "However, additional investigation into the lung-specific cellular source of the proinflammatory cytokines typical of severe COVID-19, including IL-6, tumor necrosis factor–α (TNF-α), IL-1β, and IL-17A, is needed." (PMID 33622974, 2021). "In agreement with other studies, we found that IL-6 and TNFα were elevated in the COVID-19 cohort compared to the control subjects [median (IQR), all units picograms per milliliter; IL-6: 4.65 (3.32–9.16) vs 0.69 (0.55–0.89), p < 0.001; TNFα: 4.49 (1.87–8.03) vs 0.04 (0.04–0.84), p < 0.001]." (PMID 34792686, 2021). "Furthermore, other cytokines were found to differentiate MIS-C and KD with shock or pediatric COVID-19, like IL-10 and TNFα." (PMID 34869111, 2021).